RNU6-431P (RNA, U6 small nuclear 431, pseudogene)
Gene: Small nuclear RNA gene on chromosome 4 (108,652,150 to 108,652,256, forward strand). Ensembl gene ENSG00000206601.
Homologues: Orthologues: chimpanzee U6 (99% identical), macaque U6 (95% identical). Paralogues in human: RNU6-12P (94% identical), RNU6-13P (94% identical), RNU6-32P (94% identical), RNU6-1 (93% identical), RNU6-17P (93% identical), RNU6-18P (93% identical), RNU6-19P (93% identical), RNU6-2 (93% identical), RNU6-31P (93% identical), RNU6-3P (93% identical), RNU6-4P (93% identical), RNU6-5P (93% identical), and 1289 more.